IL1B (interleukin 1 beta)
Diseases named in the same sentence as IL1B in open-access papers (continued):
Sharing a sentence is not in itself a finding about the gene and the disease.
tumor (continued). "In addition, neutrophils can also secrete bioactive substances that promote tumor progression, including VEGF, MMP9, Oncostatin M (OSM), IL-1β, ​​TNF-a, IL-8, CXCL3, ROS." (PMID 37644468, 2023). "In addition, we found that the tumor edge demonstrated increased pro-inflammatory and gliomagenic cytokines including TNF-α, IL-1β, and IL-6." (PMID 37752585, 2023). "In CAR-T-cell-treated tumor cells, the robust CAP released a large amount of ATP, which activated NLRP3-mediated inflammasome and pyroptosis in tumor-infiltrating macrophages, leading to the release of cytokines such as IL-1β." (PMID 36742298, 2023). "Tumor cells at the invasion front induce the increase of SPP1+ macrophages by expressing high levels of HLA‐G, and SPP1+ macrophages secrete IL‐1β to recruit additional SPP1+ macrophages, and together they inhibit anti‐tumor immunity by depleting other immune cells." (PMID 37632718, 2023). "Moreover, interleukin-1β (IL-1β) and tumor necrosis factor-α (TNF-α) released by NB cell-repolarized M1-Mφs can also drive tumor cell proliferation through regulating arginine metabolism." (PMID 37040518, 2023). "Some proinflammatory cytokines, such as IL-6, IL-1β, and TNF-α, are secreted by macrophages, which may contribute to tumor-promoting inflammation." (PMID 37211559, 2023). "In OSM-knockout mice, cSCC tumor volume was reduced by approximately 30% when compared to wild-type mice after one month, however there were still significant amounts of IL-6, IL-1β, IL-23α, CXCL1, IL-4, and IFNγ present in the tumor tissue compared to normal skin." (PMID 37841259, 2023). "Secondly, we quantified release of cytokines (i.e., IFNγ, IL-10, IL-2, IL-6, TNFα, GM-CSF, IL-12p70, IL-1b and IL-8) and granzyme B by using the MSD platform in supernatants collected from the TDCC assay with the tumor cell lines SK-CO-1, MKN-45 and H2122 after 48 h." (PMID 38087365, 2023). "A recent study in a mouse model of NSCLC showed that the cells of the myeloid lineage produced IL-1β irrespective of inflammasome activation, which suggests the infiltration of other immune cells to tumor sites." (PMID 37893079, 2023). "IL-1β was almost undetectable in the neocortex until the tumor cells migrated through the BBB, while its expression increased in peritumoral astrocytes in a time- and tumor size-dependent manner." (PMID 37749707, 2023). "As IL1β is an important mediator in generating CD8+ T cells, and could thus explain the increase in local CD8+ TILs in the tumor, DCs can also induce other lymphocytes." (PMID 36915084, 2023). "For example, strawberry (Fragaria ananassa) methanolic extracts have anti-inflammatory activity, reducing the levels of the tested inflammatory markers (NF-kB, pIkBa, TNF-α, IL-1b, IL-6, and iNOS) in RAW macrophages, which is an Abelson murine leukemia virus-induced tumor." (PMID 36771154, 2023). "Reciprocally, these activated HGG-AM produce IL-1β to promote GSC proliferation and tumor growth." (PMID 36594466, 2023). "Treatment with anti‐IL‐1β antibody did not affect the number of TAMs, but reduced the quantity of MDSCs and increased the number of tumor‐infiltrating CD8+ T cells." (PMID 37092583, 2023). "Several solid tumours have been found to contain elevated levels of IL-1, and individuals with IL-1β-producing tumours have a negative prognosis." (PMID 37153428, 2023). "In addition, IL-17A can promote the secretion of inflammatory factors such as IL-1β、IL-18 and immune antigens, and recruit CD8 + T cells to infiltrate tumours." (PMID 37211606, 2023). "Meanwhile, in our previous results, A3 could promote M1 polarization of macrophages in tumor tissues and increase the expression of the pro-inflammatory mediators TNF- α, IL-12, IL-6, and IL-1β." (PMID 36838599, 2023). "This TREM2+ cluster was enriched for genes linked to pro-tumor pathways and could strongly interact with FOXP3+ Tregs through the IL1B/IL1R interaction, suppressing the anti-tumor effects." (PMID 38066642, 2023).
tumor (continued). "Here, we show that PDGFB-driven GBM cells induce the expression of the potent proinflammatory cytokine IL-1β in MDM, which engages IL-1R1 in tumor cells, activates the NF-κB pathway, and subsequently leads to induction of monocyte chemoattractant proteins (MCPs)." (PMID 37733448, 2023). "NF-κB activation by tumor-secreted IL-1β induces the expression of ESE3 in PSCs, then epithelium-specific E-twenty six factor 3 (ESE3) binds to the promoters of α-SMA, collagen-I and IL-1β, activating PSCs and promoting PDAC fibrosis." (PMID 37033960, 2023). "The colocalization of GFAP- and IL-1β-positive signals was high in the tumor-bearing animals, while no detectable IL-1β was observed in the control mice." (PMID 37749707, 2023). "Furthermore, the concentration of HIF-1α in the tumor showed a significant positive correlation with CCL3 and IL-1β (p (R2) 0.007 (0.47); p (R2) 0.011 (0.38)." (PMID 38273861, 2023). "It should be noted that this radiomics model predicts IL1B expression in tumor tissue rather than serum IL1B." (PMID 36969073, 2023). "In vivo experiments revealed that HCS1 can promote the infiltration of immune cells into tumor tissues, such as neutrophils, macrophages, and dendritic cells, which further increase the secretion of pro-inflammatory cytokines, such as TNF-α and IL-1β." (PMID 37908720, 2023). "IL-1β-mediated activation of the NOD-like receptor (NLR) inflammasome plays a vital role in developing various cancers, and the blockade of IL-1β using recombinant IL-1RA significantly decreases tumor progression." (PMID 36316775, 2022). "Furthermore, IL-1β and TGF-β cooperated to elicit upregulation of stemness factor genes and augmented invasiveness and drug resistance, leading to tumor growth in vivo." (PMID 35368876, 2022). "Furthermore, when examined by qPCR, we found that the expression of immune-promoting cytokines (TNF-α, IL-1β and IFN-γ) in SU4312-treated tumor tissues was significantly higher than that in the control group." (PMID 36013004, 2022). "In the tumor microenvironment, flow cytometry analysis showed that among immune cells, pro-IL-1β was mainly expressed by myeloid cells as no expression was detected in T cells or in CD45- cells." (PMID 36104342, 2022). "Therefore, upregulation of IL-1β can contribute to the change of TME immunophenotype, the appearance of immunosuppressive tumor niche, cancer cell immune evasion, and facilitate tumor progression." (PMID 35884974, 2022). "We report a mechanism of DTX resistance in HNSCC mediated by the secretion of IL-1β from macrophages to induce ICAM1 expression, which enhances the stemness of tumor cells and promotes PGCC formation in response to DTX treatment, thereby leading to increased chemoresistance." (PMID 36264639, 2022). "Second, analyses performed on tumor lysates revealed that chemokines involved in myeloid cell migration (CCL5, CCL2, CCL4), together with inflammatory (IL-1β and TNFα) and pro-angiogenic factors (VEGF-A, VEGFR2, PDGF, Endoglin) were increased in tumors of mice fed a HFHCD." (PMID 36104342, 2022). "Free radical scavenging activities of CUR, as well as a decrease in the expression of inflammatory cytokines IL-1b, IL-6, and TNF- α, result in decreased cancer growth and down-regulation of enzymes such as protein kinase C, which regulate inflammation and tumor cell proliferation." (PMID 35159669, 2022). "Reduced expansion of JAM-A+ cells was likely not due to different tumor burden in Il1b-/- mice, as only LLC tumors but not Py8119 tumors showed altered tumor weight in IL1β-deficient mice." (PMID 36531986, 2022). "CASP8, CASP6, GSDME, NOD1, and GPX4 were significantly upregulated in tumor tissues compared to the normal tissues, whereas IL6, IL1B, NLRP3, and NLRC4 were downregulated, suggesting that pyroptosis-related genes play important roles in tumor progression and prognosis." (PMID 35559014, 2022).
tumor (continued). "We show that NFKBIZ mRNA is low to undetectable in unstimulated tumor cells while it is induced by IL1β in two different ccRCC cell lines, although it was not increased in a dose-dependent manner." (PMID 35814450, 2022). "Within the tumor, only 3 mononuclear phagocytes - CD16+ monocytes, NLRP3+ macrophages, and INHBA+ macrophages – had elevated levels of NLRP3 and IL1B expression." (PMID 36439171, 2022). "In many cases, the inflammatory TME contributes to metastasis by recruiting blood and lymph vessels, such as the S1PR1 on tumor-associated macrophages (TAMs), which triggers lymphangiogenesis, tumor angiogenesis, and metastatic spread via NLRP3/IL-1β in pulmonary cancer." (PMID 35892884, 2022). "Considering the results of gene expression microarray analysis in our previous study, we selected IL-1α, IL-1β, CXCL1, and IL-8 as candidates that may be responsible for tumor-induced osteoclastogenesis (red bars)." (PMID 36614130, 2022). "Extensive research has shown that intestinal microbes stimulate the expression of chemokines such as TNF- α, IL-6, IL-10, and IL-1β or activate cytotoxic lymphocytes, such as CD4+ and CD8+ T cells or NK and NKT cells, in both peripheral blood and tumor to limit tumor growth." (PMID 36232344, 2022). "Regardless of tumor type, patients with values of sTIM3, IFNα, IFNγ, IL1β, IL1α, IL12p70, MIP1β, IL13, sCD28, sGITR, sPDL1, IL10 and TNFα below the median had longer overall survival (p<0.05)." (PMID 36405727, 2022). "Our data confirmed that IL-1β can be expressed in PDAC cell lines, and the secreted IL-1β in tumour CM was remarkably upregulated after Gem treatment, which may be the reason for the secondary chemoresistance." (PMID 35986089, 2022). "As we know, IL-1β and TNF-α are important in the tumor microenvironment." (PMID 36016583, 2022). "In addition, luteolin treatment (50 mg/kg/day i.p. injected) increased ASC, cleaved caspase-1, IL-1β, and NLRP3 protein levels in xenografts of HT-29 cells in nude mice, simultaneously decreasing tumor size." (PMID 36555392, 2022). "Our study revealed another lncRNA KCNQ1OT1/miR-328-3p/IL1B regulatory axis in LUSC, which may also play a vital function in the tumor progression." (PMID 35692583, 2022). "On the one hand, pyroptosis, a lytic and proinflammatory type of regulated cell death, is characterized by cell swelling, lysis, and the release of numerous proinflammatory factors, including IL-18, ATP, IL-1β, and HMGB1, which can promote tumor growth and progression." (PMID 35784306, 2022). "In patients with advanced tumors, some inflammatory factors such as tumor necrosis factor alfa, interleukin 6, and interleukin 1 beta can induce the synthesis of CRP in hepatocytes while promoting angiogenesis to support tumor growth and anti-apoptosis capabilities to protect tumor cells." (PMID 36266627, 2022). "Compared with the control and Lmo treatments, the tumor‐bearing mice treated with Lmo@RBC displayed an obviously high level of IL‐6, IL‐1β, and TNF‐α in blood serum, which was attributed to the high‐efficiency tumor‐homing capability of Lmo@RBC to improve the therapeutic efficiency." (PMID 36266982, 2022). "In addition, IL-1β secreted into the TME is mainly proinflammatory and promotes tumorigenesis, tumor invasiveness, and immunosuppression." (PMID 35884397, 2022). "Furthermore, C3a and C5a are efficient stimulators of inflammatory mediators like IL-1β, IL-6 and TNF-α, and inflammatory processes are vital for tumor development, promoting subthreshold neoplastic tumor states to fully cancerous states." (PMID 36547187, 2022). "IL-1β also increases cell numbers and infiltration of MDSC in tumor." (PMID 35739593, 2022). "Some crucial cytokines, including G-CSF, IL-1β, VEGF, and IL-6 from tumor cells, could potentially increase the number of neutrophils in peripheral blood and tumor tissue." (PMID 36556130, 2022).
tumor (continued). "Furthermore, the reduction of IL-1β can be directly related to ROS reduction, also induced by treatment with ACS-AZ, since ROS can directly affect the tumor microenvironment by releasing inflammatory cytokines, among them IL-1β." (PMID 36324671, 2022). "Additionally, expansion of immunosuppressive B cells induced by IL-1β might promote PAAD57, and many extracellular matrix (ECM) components, including collagen, growth factors, cytokines, chemokines, and cancer-associated fibroblast (CAF) play vital role in tumor progression." (PMID 35831362, 2022). "Another study in head and neck squamous cell cancer indicated that IL-1β could be activated by NLRP3 that is related to the anti-tumor immune responses and tumor progression." (PMID 36276158, 2022). "Moreover, nitric oxide (NO) released by the fibroblasts can induce IL-1β secretion in PDAC cells, which binds to its receptor expressed on tumor cells to confer chemoresistance in a paracrine manner." (PMID 36230914, 2022). "TNF-α, IL-10, and IL-1β mimicked the effects of TSN in inducing the upregulation of CA12 expression in monocytes, and consistently, anti–TNF-α, anti–IL-10, and anti–IL-1β antibodies attenuated the induction of CA12 in tumor-exposed monocytes." (PMID 35362480, 2022). "In the current study, we found that many of IL1 signaling molecules (e.g., IL1α, IL1β, IL1R1, IL1RAP, IL36, IL36R and IRAKs) were highly activated during KSHV infection or in KSHV+ tumor cells and tissues, indicating the crucial role of these molecules functions in KSHV pathogenesis and oncogenesis." (PMID 36457850, 2022). "A recent elegant study demonstrates that, in basal-like BC, Notch not only regulates cancer cell expression of the mononuclear cell chemokines IL-1β and CCL2, but also facilitates TGF-β-mediated activation of tumor cells by TAMs, closing a signaling loop between these two cell types." (PMID 35682974, 2022). "KD reduces the production of pro-inflammatory cytokines, including tumor necrosis factor-α (TNF-α), interleukin-1β (IL-1β), interferon-γ (IFN-γ), and cyclo-oxygenase 2 (COX-2), which are involved in tumor growth, proliferation, angiogenesis, invasion, metastasis, and DNA damage." (PMID 36139562, 2022). "In addition, we validated the correlation between Il1B expression and TME profile in tumor tissue derived from patients with LUAD." (PMID 35471938, 2022). "We showed that deletion of NLRP3, but not AIM2, phenocopied caspase-1/IL-1β dependent tumor progression in vivo." (PMID 36439171, 2022). "Therefore, the activities of cDC-CD1C-AREG, macrophage-IL1B and Mono-FCGR3A in low tumor infiltration group were elevated as innate immune cells and APCs, but suppressed in high tumor infiltration group." (PMID 36532059, 2022). "MRNA levels of CA12 exhibited positive correlations with those of HIF1A, TNF-A, IL-10, and IL-1B, but not those of IL-6, in tumor-derived monocytes." (PMID 35362480, 2022). "In addition, pro-inflammatory cytokines (e.g., IL-6, TNF-α, and IL-1β) induced by ICD, can also help convert an immunosuppressive tumor microenvironment into an immunogenic one." (PMID 36278159, 2022). "(ii)In addition to participating in purinergic neurotransmission, ATP released from damaged cells can bind to the P2Y2 receptor of macrophages, promoting the infiltration of macrophages in tumor sites, and can also bind to the P2RX7 of DC cells, leading to DC maturation and release of IL-1β." (PMID 36081554, 2022). "Furthermore, the elevated inflammatory cytokine IL-6 can raise tumor progression and invasion in GBM, and high levels of IL-1β also activate GBM cells and promote IL-6 production." (PMID 35368876, 2022). "However, Mono-FCGR3A in high tumor infiltration group expressed lower levels of MHC molecules, inflammatory cytokines and chemokines (HLA-DRB1/HLA-DPB1, TNF, IL1B, CCL3 and CCL4), which meant the sub-cluster was less involved in immune responses." (PMID 36532059, 2022).
tumor (continued). "Notably, IL1B, NDRG1 and TIMP1 act as drivers of ferroptosis, and their low expression in patients with poor prognosis implies a correlation between tumor cell resistance to ferroptosis mechanisms and poor prognosis." (PMID 36226170, 2022). "Pro-inflammatory cytokines secreted by tumor cells or stromal cells, such as interleukin 6 (IL6), IL1β and C-C motif chemokine ligand 2 (CCL2), can induce phenotypic changes in tumor cells, recruit bone marrow-derived cells and form an inflammatory environment." (PMID 36158661, 2022). "We found that myeloid intrinsic NLRP3-mediated activation of caspase-1 and subsequent IL-1β release is permissive towards tumor growth, and that caspase-1 regulates the survival but not trafficking of the myeloid cells to the TME." (PMID 36439171, 2022). "Inhibited the expression of PPP2CA, which could promote the release of pro-inflammatory cytokines such as IL-1b, IL-6, and TNF-a from macrophages stimulating tumor invasion." (PMID 36612080, 2022). "Therefore, pyroptosis plays an anti-tumor role in the process of tumor formation, while HPV inhibits the progression of pyroptosis by suppressing the expression of IL-1β, IL-18 and inflammasomes, thus promoting tumor progression." (PMID 36497244, 2022). "STAT3 silencing also could reduce the expressions of cytokines IL-6, IL-1β and inflammatory mediators ICAM1 and COX2 in the tumor microenvironment." (PMID 35513871, 2022). "As one of the dominant cell types in the inflamed intestine, macrophages produce various cytokines, including IL‐6, IL‐12, IL‐23, IL‐1β and TNF, which modulate IEC activity and immune responses and evolve with and provide support to tumour cells during the transition to malignancy." (PMID 35363937, 2022). "According to the clustering results, C1q+ TAMs, SPP1+ TAMs, and CCL20+IL1B+ macrophages were substantially more abundant in tumor tissue than in non-malignant colorectal tissues." (PMID 36172359, 2022). "Moreover, IL17 production, due to an increased Th17 cell number, induces osteoblast cell death through pyroptosis with the release of IL1β and cooperates with RANKL to further activate osteoclasts enhancing tumor growth and promoting MBD in MM." (PMID 35954459, 2022). "IL-1β, a typical cytokine secreted by M1-type macrophages, also does not necessarily act favorably in tumor treatment or as a biomarker for good prognosis." (PMID 36430236, 2022). "Therefore, we tested the effects of si-m/hVDAC1-B tumor treatment on the expression of NRLP3, activated caspase 1, and IL-1β." (PMID 35883451, 2022). "Petrilli and colleagues reported an immunosuppressive role of the Nlrp3-Asc-Caspase-1 pathway, that blunted NK cell tumor recruitment and activation, but that was independent of IL-1β, IL-18 or IL-1 receptor signaling." (PMID 35517498, 2022). "Of the commonly enriched factors, FGF7, but not IL1B, showed significant effect on the proliferation of radiated tumor cells." (PMID 36261421, 2022). "Normal and tumour tissues from such patients were analysed by qRT-PCR for the following 12 genes; six from RNA-seq: CLDN1, MAGEB2, CD24, CEACAM6, IL1B and ISG15 and six from RNA-seq and proteomics cross-linking: AKR1C3, TNFAIP2, RAB7A, LGALS3BP, PSCA and SSRP1." (PMID 36428603, 2022). "Taken together, our findings indicate that IL1B-expressing macrophages (TR Mac.2) are co-localized with EMThigh RCC cells macroscopically and microscopically both at the tumor-normal interface and in the tumor core." (PMID 36423636, 2022).